NOTCH3 (notch receptor 3)
Diseases named in the same sentence as NOTCH3 in open-access papers (continued):
Sharing a sentence is not in itself a finding about the gene and the disease.
breast carcinoma (continued). "Western blot analyses showed that Notch1 and Notch3 as well as all three Pim family kinases are expressed in MCF-7 breast cancer cells, whereas PC-3 prostate cancer cells express all but Notch3." (PMID 27281612, 2016). "We also shed light on the underlying molecular mechanism by which ectopic overexpression of Notch3 can reverse EMT in breast cancer epithelial cells." (PMID 27841855, 2016). "These analyses revealed positive Pearson correlations between PIM1 and NOTCH1 in both types of cancer as well as between PIM1 and NOTCH3 in breast cancer." (PMID 27281612, 2016). "Western blotting revealed that the expression levels of Notch3 and E-cadherin varied among the five breast cancer cell lines." (PMID 27841855, 2016). "To further understand the role of Kibra in Notch3-induced EMT inhibition in breast cancer cells, we constructed a Kibra expression vector, pEZ-Lv105/Kibra." (PMID 27841855, 2016). "In this way, stromal cells can activate the Notch3 pathway in breast cancer cells; then, stromal cells can release exosomes to coordinate with Notch3, thus promoting the proliferation of those resistant cancer cells." (PMID 27686593, 2016). "Recent report showed that IL-6 activated Notch3 signaling also induced CD133 overexpressing cells in breast cancer and further investigations are warranted." (PMID 27489358, 2016). "The molecular profile analysis of breast cancer stem tumorigenic cells revealed an upregulation of IL-6 and of Notch-3, a stem cell regulatory gene." (PMID 25881039, 2015). "Here, we show that Notch-3-dependent ERK activation in breast cancer via IL-6 targets the activation of Jagged-1, which belongs to a family of Notch ligands and CA-IX, a hypoxia survival gene." (PMID 25881039, 2015). "Although most studies have been utilized Notch1 as the readout of Notch signaling, the four Notch receptors, Notch1, Notch2, Notch3 and Notch4, are thought to have different functions in breast cancer." (PMID 25229616, 2014). "When primary breast cancer samples are examined, accumulation of activated Notch1 and Notch3 is frequently observed in tumor cells." (PMID 25309874, 2014). "NOTCH3, which has been shown to play a role in maintenance of stemness in breast cancer cells, was also more highly expressed in the tamoxifen-resistant versus parental cell lines." (PMID 24355041, 2013). "Collectively, our findings suggest that NOTCH3 signaling is crucial for the proliferation of glioma cells which is consistent with previous studies in other cancers such as lung and breast cancer." (PMID 24143218, 2013). "Since miR-206 is known to target Notch3 expression in breast cancer, Notch3 expression levels in miR-206 transfected cells were assessed via immuno-blotting." (PMID 23071643, 2012). "Real-time PCR and Western blot analysis were performed to detect Notch-1, Notch-2, Notch-3 and Notch-4 receptor expression in breast cancer cells when PEA3 was knocked down by siRNA." (PMID 21679465, 2011). "In HER2- breast cancers, downregulation of Notch-3 resulted in suppressed proliferation and increased apoptosis." (PMID 21679465, 2011). "Overexpression of constitutively active forms of Notch-1, Notch-3, and Notch-4 develop spontaneous murine mammary tumours in vivo." (PMID 21847123, 2011). "Transgenic mice overexpressing active Notch1, Notch3, or Notch4 homologs all developed mammary carcinoma." (PMID 19660128, 2009). "Surprisingly, we also detected intense nuclear staining for Notch3 in some breast cancers using the N-terminal specific antibody, suggesting possible nuclear translocation of full length Notch3." (PMID 20030805, 2009). "NOTCH3 over-expression also has been shown to play a major role in the proliferation of ERBB2-negative breast cancer cells." (PMID 20040092, 2009). "In breast cancer, Notch3 primarily functions as an oncogene, with a few exceptions." (PMID 41027955, 2025).
breast carcinoma (continued). "Similarly, in ErbB2-negative breast cancer models, Notch3 exerts oncogenic effects through the canonical CSL-dependent transcriptional regulatory mechanism." (PMID 41050674, 2025). "Interestingly, MDH2 overexpression upregulated several genes associated with breast cancer metastasis (IL13RA2, MMP3, PTGS1, SYK, VCAN, and FLT1) and downregulated several genes associated with metastasis suppression (NOTCH3 and HTRA3)." (PMID 41179294, 2025). "Notably, Notch3 expression has been linked to EMT-induced cancer cell plasticity and the emergence of lung metastases in breast cancer models." (PMID 39766289, 2024). "This investigation further describes the possible role of NOTCH3/miR-223/ZEB1 in breast cancer." (PMID 38164285, 2024). "It’s interesting to note that in terms of the prognosis and survival connection of patients with breast cancer, the expression level of NOTCH3 in the Kaplan–Meier plotter database produced findings that were comparable to those in the GEPIA database (RFS HR = 0.88, 95% CI = 0.79–0.97, P = 0.0095)." (PMID 38906903, 2024). "Overexpressing the intracellular domain of NOTCH3 (N3ICD) can up-regulate the expression of Cdh1 and cause p27Kip accumulate by accelerating the degradation of Skp2, as well as inhibit the breast cancer cell line, MDA-MB-231, proliferation and colony formation rate." (PMID 38906903, 2024). "Previously, it has been reported that the expression of NOTCH3 is positively correlated with a lower Ki-67 index and the incidence of involved lymph node status in breast cancer patients, and predicts a better recurrence-free survival rate of breast cancer patients." (PMID 38164285, 2024). "However, further experimental design and research are needed to verify the effect of NOTCH3/miR-223/ZEB1 axis on breast cancer at the animal and clinical levels." (PMID 38164285, 2024). "In addition, NOTCH3 up-regulates the expression of GSK3β, which is related to better recurrence-free survival rate of all breast cancer patients." (PMID 38164285, 2024). "It should be noted that the effect of NOTCH3 in breast cancer has also been reported." (PMID 38164285, 2024). "This show that HeyL is a direct target of Notch3 in breast cancer cell lines." (PMID 36854682, 2023). "Further exploration demonstrated that low expression of STAT5A and Notch3 both predict poor survival of breast cancer patients, which may be related to the suppressed immune response." (PMID 38124049, 2023). "Similarly, in transwell assays, Notch3-mediated inhibition of cell migration and invasion of breast cancer cells was partially reversed by suppressing the Notch3 downstream target STAT5A." (PMID 38124049, 2023). "Next, we sought the mechanism(s) by which Notch3 expression was reduced in breast cancer." (PMID 36854682, 2023). "As expected from previous studies, Notch3 protein staining in the breast cancer epithelial compartment was weak (only 28.6% of tumor tissues had a strong staining intensity compared to 75% (15/20) of the normal tissues), whereas it was strong in stromal cells and in the vascular system." (PMID 36854682, 2023). "We observed a significant increase in patient survival when Notch3 expression was strong in tumor cells, whereas stromal expression had no impact on survival, arguing in favor of a tumor cell-intrinsic role for Notch3 in breast cancers." (PMID 36854682, 2023). "The tumor suppressor gene, PTEN, was reported as a Notch3 downstream target to suppress cell proliferation and tumorigenesis in breast cancer, while Kibra-mediated Hippo/YAP signaling was also transcriptionally activated by Notch3 in breast cancer epithelial cells to inhibit EMT process." (PMID 38124049, 2023). "For example, while Notch3 signaling exhibits the oncogenic potential in a murine breast cancer model and promotes luminal breast cancer metastasis, overexpression of Notch3 inhibits proliferation and metastasis in TNBC and is associated with better survival in TNBC patients." (PMID 37149651, 2023).
breast carcinoma (continued). "Having correlated Notch3 expression with good breast cancer patient prognosis, we wondered whether Notch3 signaling could limit cancer cell transformation." (PMID 36854682, 2023). "Ectopic STAT5A knockdown partially restored the migration and invasion of breast cancer cells, following Notch3 overexpression-induced suppression, indicating that Notch3-mediated inhibition of breast cancer metastasis occurs in part through activating STAT5A expression." (PMID 38124049, 2023). "Moreover, overexpressing STAT5A partially reversed the enhanced mobility of breast cancer cells following Notch3 silencing." (PMID 38124049, 2023). "We therefore conclude that a Notch3-HeyL-Mybl2 axis limits proliferation in breast cancers." (PMID 36854682, 2023). "In summary, our preliminary results suggested that Notch3 might inhibit EMT by trans-activating GSK3β in breast cancer cells." (PMID 36139447, 2022). "Our previous studies have shown that Notch3 also inhibits EMT in breast cancer." (PMID 36139447, 2022). "Remarkably, this finding demonstrates for the first time that Notch3 may inhibit the EMT process in breast cancer cells through transcriptionally upregulating GSK3β." (PMID 36139447, 2022). "Similarly, NOTCH2 and NOTCH3 act as promoters in breast cancer, pancreatic ductal adenocarcinoma, and lung cancer." (PMID 36517618, 2022). "N3ICD overexpression downregulates the mesenchymal phenotype marker and upregulates the epithelial marker, which suggests that Notch3 may inhibit the progression of EMT in breast cancer." (PMID 36139447, 2022). "Meanwhile, previous research proved that breast cancer tumorigenesis could be regulated by phosphorylation of Notch3, which might be affected by PTEN transactivation." (PMID 36072578, 2022). "The suppression of Notch3 expression may contribute to EMT by transcriptionally downregulating GSK3β in breast cancer." (PMID 36139447, 2022). "The purpose of this study was to investigate whether Notch3 acts as a transcriptional activator of GSK3β in breast cancer." (PMID 36139447, 2022). "Nevertheless, several studies have indicated that Notch3 may play a role in inhibiting tumor development in breast cancer." (PMID 36139447, 2022). "Finally, over-expression of both Notch3 and GSK3β mRNA was found to be associated with better recurrence-free survival (RFS) in all patients with breast cancer." (PMID 36139447, 2022). "In order to verify whether Notch3-PTEN high expression could predict the prognosis and survival of breast cancer patients, we analyzed the prognosis of patients with high or low Notch3 or PTEN mRNA expression from the open database, Kaplan-Meier Plotter." (PMID 34006834, 2021). "Furthermore, hypoxia-inducible factor 1α (HIF1α) downregulated breast CSCs by reducing the IL-6 levels in breast cancer cells expressing Notch3." (PMID 33673088, 2021). "Therefore, our findings demonstrate that Notch3 inhibits breast cancer proliferation and suppresses tumorigenesis by transactivating PTEN expression." (PMID 34006834, 2021). "Therefore, the tumor suppressive function of CBFB in breast cancer includes several mechanisms, TAp73 activation, NOTCH3 repression, and other yet unidentified genes or signaling pathways." (PMID 33945523, 2021). "In Chinese population, while the association of NOTCH2-rs11249433 and NOTCH3-rs1043994 was lacking with breast cancer risk, NOTCH1-rs3124591 was significantly associated with invasive ductal carcinoma and ductal carcinoma in situ." (PMID 34257585, 2021). "Interestingly, the level of Notch3 mRNA and protein levels were higher in luminal-type (ER-positive) breast cancer and lower in ER-negative breast cancer." (PMID 34006834, 2021). "Interestingly, another receptor, NOTCH3, promotes bone metastasis of breast cancer but inhibits its lung metastasis." (PMID 34374886, 2021). "The objective of this study was to determine whether Notch3 is a direct transcriptional activator of PTEN in breast cancer." (PMID 34006834, 2021).
breast carcinoma (continued). "Previous studies by our group demonstrated that Notch3 may inhibit the emergence and progression of breast cancer." (PMID 34006834, 2021). "NOTCH3 has been previously demonstrated to bind to promoters of breast cancer genes." (PMID 33858322, 2021). "Indeed, PROM1 has been shown to mediate endocrine therapy resistance in breast cancer models through IL6/Notch3 signaling." (PMID 33407744, 2021). "Our previous study found that CBFB suppresses breast cancer partially through NOTCH3 repression." (PMID 33945523, 2021). "Notch3 expression was strongly negative associated with FSCN1 levels in breast cancer tissues (r = −0.248, p = 0.010)." (PMID 33099573, 2020). "Our findings illustrated that Notch3 signaling activation is necessary for the development of the mammary gland, but its hyperactivation closely relates to breast cancer progression, and that Notch3-regulating CCL2/CCR4 axis should be the target for breast cancer therapy." (PMID 33244467, 2020). "The depletion of NOTCH3 in luminal breast cancer cells promoted metastasis in vivo." (PMID 32210163, 2020). "Meanwhile, the renewal of cancer stem cell could be induced by IL-6 through Notch3 in breast cancer." (PMID 32028262, 2020). "Thus, the current results uncover a novel molecular mechanism of the Notch3/miR-488/FSCN1 axis in breast carcinomas." (PMID 33099573, 2020). "Importantly, the regulating effect of miR-488 can be modulated by the expression of Notch3, to regulate the proliferation and motility of breast cancer cells." (PMID 33099573, 2020). "To investigate the potential role of Notch3 signaling in breast cancer cells, we, respectively, established stable N3ICD- as well as TD+N3ICD-overexpressing transfectants in low Notch3-expressing MDA-MB-231 cells by transfecting pCLE/N3ICD or pCMV-(TD+N3ICD) plasmids." (PMID 31096822, 2019). "The purpose of this up-to-date review is to provide a detailed overview of the specific role of all four Notch receptors (Notch1, Notch2, Notch3, and Notch4) in TNBCs, thus identifying the Notch signaling pathway deregulation/activation as a pathognomonic feature of this breast cancer subtype." (PMID 31379945, 2019). "In addition, Notch3 pivotal role in the proliferation of ErbB2-negative breast cancer cell lines has been demonstrated." (PMID 31379945, 2019). "Reedijk and colleagues pointed out that Jagged1 and Notch3 are overexpressed in blood vessels of primary breast cancer, but little is done to understand whether Jagged1 and Notch3 are closely related to angiogenesis in TNBCs." (PMID 31379945, 2019). "NOTCH3 has also been reported as a major driver for breast cancer development." (PMID 31552087, 2019). "Simultaneously, the stromal cells induced activation of NOTCH3 on breast cancer cells." (PMID 31146452, 2019). "Importantly, the majority of vMCF-7∆Raf1 1GX-M cells were strongly positive for NOTCH3 staining by immunofluorescence assay, demonstrating that NOTCH3 expression was restricted to clonal metastatic breast cancer cells." (PMID 30180881, 2018). "Our observation of pro-invasive actions of RA in MDA-MB-231 breast cancer cells is in apparent contradiction with our previous finding that RA downregulated putative pro-invasive molecules such as i21VEGFR-1 and Notch-3, and upregulated putative anti-invasive molecules as miR-200c19,23,24." (PMID 29728589, 2018). "Due to the important roles of Notch3 and GATA-3 as epithelial phenotype markers of breast cancer, we hypothesized that the Notch3/GATA-3 axis modulates the expression of EMT markers." (PMID 30100605, 2018). "In addition, IL-6 derived from metastatic CAFs triggered breast cancer growth in vitro and in vivo through the involvement of Notch-3, Jagged-1, and the HIF-1α target gene carbonic anhydrase IX." (PMID 29996493, 2018). "Interestingly, NOTCH3 signaling appears to be constitutive, i.e., ligand-independent, in breast cancer cell lines, which makes it interesting as a therapeutic target." (PMID 30388742, 2018).
breast carcinoma (continued). "Whereas vMCF-7Raf-1 1GX MPS lacked nuclear ERα expression, partial restoration of nuclear ERα expression was observed in vMCF-7Raf-1 1GXCRISPR-NOTCH3 MPS, corroborating the role of the NOTCH3 signaling pathway in restraining ERα expression in breast cancer cells." (PMID 30180881, 2018). "Since our data showed an inverse correlation between miR-221 or miR-222 and Notch3 expression in breast cancer cells, we speculated that Notch3 might be a target of miR-221/222." (PMID 30109262, 2018). "To define in a different breast cancer model whether increased expression of NOTCH3 was restricted to metastatic cancer cells, we employed MDA-MB-231 TNBC cells that exhibit a CD44high/CD24low basal-like phenotype and elevated endogenous MAPK activity." (PMID 30180881, 2018). "Endocrine resistant breast cancers show increased BCSCs numbers with Notch3/4 expression." (PMID 30515368, 2018). "To investigate the mechanism of Notch3 down-regulation in basal-like breast cancer cell lines, we performed bioinformatic searches (including Pictar, DIANAmT, miRanda, miRWalk and RNAhybrid databases) to identify putative microRNAs targeting Notch3." (PMID 30109262, 2018). "For instance, using mammosphere assay as a readout for CSCs activity, Sanguinetti and coworkers found that IL-6 induces stem-like features by stimulating the Notch-3-dependent upregulation of the carbonic anhydrase IX gene and promoting a hypoxia-resistant/invasive phenotype in breast cancer cells." (PMID 29996493, 2018). "NOTCH3 may also play a role in breast cancer metastasis, as Notch3 expression in breast cancer is important for osteoblast differentiation and TGFβ production as well as for regulation of metastasis to the bone." (PMID 30388742, 2018). "Moreover, using a reporter assay and a ChIP assay, our study demonstrates that Notch3 is capable of binding to CSL-binding motifs in the promoter of GATA-3 in breast cancer cells, suggesting that N3ICD directly activates GATA-3 expression." (PMID 30100605, 2018). "Moreover, diet-induced obesity, which increased leptin levels and signaling in mice hosting mammary tumors, incremented the levels of Notch3, JAG1 and survivin." (PMID 30004402, 2018). "Moreover, IL-6 promotes breast cancer bone metastasis through Notch-1, and induces mammosphere formation in breast cancer cells through Notch-3." (PMID 28270211, 2017). "Consequently, further study is necessary to fully elucidate the role of Notch3 signaling in breast cancer." (PMID 27841855, 2016). "Collectively, our findings demonstrate that Kibra is necessary for maintaining normal expression of Notch3 in breast cancer epithelial cells, but an additional signal may be required to fully regulate Notch3 expression." (PMID 27841855, 2016). "Taken together, these data indicate that Notch3 may have an inhibitory role during EMT in breast cancer." (PMID 27841855, 2016). "To investigate whether there is any interaction between Notch3 and Kibra in breast cancer epithelial cells, we first analyzed the expression of Notch3 when overexpressing or knocking down Kibra." (PMID 27841855, 2016). "Analyses in HCC1937 breast cancer cells showed similar outcomes of NAC inhibition of Notch3-mediated malignancy as those in HeLa cells, including NAC-induced decrease in N3IC protein level and rescue of NAC-inhibited proliferation, migration and invasion by N3ICD." (PMID 27102435, 2016). "Interestingly, in this study, one of the most remarkable findings is the heterogeneity of Notch3 expression in various breast cancer cell lines." (PMID 27841855, 2016). "We therefore hypothesized that, in total contrast to Notch1, Notch3 may act to inhibit EMT in breast cancer epithelial cells." (PMID 27841855, 2016).